NRP1 (neuropilin 1)
Diseases named in the same sentence as NRP1 in open-access papers (continued):
Sharing a sentence is not in itself a finding about the gene and the disease.
non-small cell lung carcinoma (28 papers, 2008 to 2025). A group of at least three distinct histological types of lung cancer, including non-small cell squamous cell carcinoma, adenocarcinoma, and large cell carcinoma. "In murine non-small cell lung carcinoma models, targeting NRP-1 with anti-NRP simultaneously with anti-VEGF therapy resulted in more effective tumor growth reduction." (PMID 38468231, 2024). "Monoclonal antibodies against NRP1 have an additive effect with anti-VEGF therapy to inhibit the growth of non-small cell lung cancer (NSCLC) xenografts in mice." (PMID 37894289, 2023). "NRP1 can also contribute to the resistance to radiotherapy as demonstrated by experiments in non-small-cell lung cancer cells." (PMID 37894289, 2023). "Second, Neuropilin-1 (NRP1) has been reported to be highly expressed in non-small-cell lung cancer cells (NSCLCs) and to play a key role in the occurrence, development and metastasis of NSCLC40." (PMID 32678190, 2020). "Here we show that Nrp-1 is expressed on a subset of human CD8+ TIL in non-small-cell lung cancer (NSCLC) tumours and on murine CD8+ TIL from several tumour types." (PMID 31350404, 2019). "In fact, it has been reported that NRP1 silencing in non-small cell lung cancer (NSCLC) Calu-1 cells increases significantly the apoptotic rate and the sensitivity to ionizing radiation (IR), compared to controls." (PMID 31027288, 2019). "It has also been reported that NRP-1 is an independent predictor of cancer relapse and poor survival in patients with non-small cell lung cancer, similar to our finding in our population of SCCHN." (PMID 23563900, 2013). "For example, Nrp1 positivity by tumor cells was recorded in 6% of primary and 14% of metastatic breast cancers, and 36% of primary and 50% of metastatic non-small-cell lung carcinomas (NSCLCs)." (PMID 22948112, 2012). "NRP1 was also significantly correlated with poor prognosis in non-small-cell lung carcinomas, and blocking VEGF and NRP1 significantly increased survival." (PMID 18781179, 2008). "Similarly, knockdown of NRP1 showed an increase in the radiosensitivity of human non-small-cell lung cancer cells (NSCLC), not only in vitro, but also in vivo, perhaps via the VEGF-PI3K-NF-kappaβ pathway." (PMID 36457009, 2022). "Finally, we only investigate the mechanistic role of NRP1 in the radiation resistance of non-small cell lung cancer cells, other tumors will be explored in future studies." (PMID 34539883, 2021). "For instance, in non-small-cell lung cancer (NSCLC), NRP1 was significantly increased and functioned as a vital promoter of metastasis." (PMID 39334861, 2024). "In patients with non-small cell lung cancer (NSCLC), high expression of NRP1 has shorter overall survival than in patients with low expression of NRP1." (PMID 35600336, 2022). "Blocking NRP1 function produced a synergistic effect with that of anti VEGF, leading to inhibition of non-small-cell lung cancer (NSCLC) growth, which suggests that NRP1 may be a potential target for improving the efficacy of anti-VEGF therapy." (PMID 25954957, 2015). "The purpose of this study was to determine the correlation between over-expression of the neuropilin 1 (NRP1) gene and growth, survival, and radio-sensitivity of non-small cell lung carcinoma (NSCLC) cells." (PMID 26147006, 2015).
ovarian carcinoma (27 papers, 2007 to 2024). A malignant neoplasm originating from the surface ovarian epithelium. "In malignant tumors, the expression of NRP has also been confirmed in lung, pancreatic, prostate, breast, and ovarian cancer cells, and NRP-1 plays a mediator in tumor development associated with tumor initiation, tumor growth, and angiogenesis." (PMID 34698100, 2021). "miR-200c sensitizes Olaparib-resistant ovarian cancer cells by targeting Neuropilin 1, which has been shown to promote unlimited growth through the evasion of contact inhibition." (PMID 36499626, 2022). "This is supported by an earlier study, which demonstrated that NRP-1 upregulation in ovarian cancer indicated poor prognosis when analysing tissue, gene and protein expression levels." (PMID 36338759, 2022). "It was proposed that high NRP-1 expression in the primary tumor predicts poor prognosis in ovarian cancer patients." (PMID 36338759, 2022). "Recent studies have additionally demonstrated a role of Neuropilin 1 (NRP1) in response to ovarian cancer therapies." (PMID 34072593, 2021). "Significant levels of cell-surface αvβ3 and NRP-1 were detected in OVCAR-8 ovarian cancer cells, HEI-193 human vestibular schwannoma cells, and human primary VS cells from 4 different tumors." (PMID 29018206, 2017). "In this process, as suggested by in vitro and in vivo ovarian cancer experiments, it probably mediates adhesion to the peritoneum by interacting with mesothelial neuropilin 1 (NRP1)." (PMID 27074785, 2016). "We show for the first time, that NRP-1 is a blood-based prognostic biomarker, which could be easily implemented into routine clinical diagnostics of ovarian cancer." (PMID 36338759, 2022). "NRP-1 up-regulation in ovarian cancer tissue predicts poor prognosis." (PMID 36338759, 2022). "Both the pro-angiogenic activity of NRP-1 and its link to PARPi resistance would strongly suggest a potential use as a suitable auxiliary marker for predicting response to the combination of bevacizumab/olaparib in patients with ovarian cancer." (PMID 36338759, 2022). "Additionally, ectopic miR-200c expression can increase apoptosis and weaken the resistance to olaparib in the ovarian cancer cells SKOV3/PARPi by silencing Neuropilin 1 (NRP1)." (PMID 34512721, 2021). "In addition, NRP1 has been reported to be a valuable prognostic marker and a potential molecular therapeutic target for ovarian cancer patients." (PMID 32678190, 2020). "Firstly, we performed qRT-PCR to assess the mRNA expression of NRP1 in ovarian cancer specimens." (PMID 31898520, 2020). "However, the clinical relevance of the soluble form of NRP-1 (sNRP-1) as a circulating biomarker in ovarian cancer patients is unknown." (PMID 36338759, 2022). "In ovarian cancer, L1CAM-ECD interacts with to α5β1, αvβ5, and αvβ3 integrins, and with NRP-1, the latter of which allows for binding the mesothelium." (PMID 31455004, 2019). "To visualize the internalization and postendocytic trafficking of the α5β1/Nrp1 complex, we deployed the photoactivatable (PA) α5-GFP (α5-PA-GFP) probe that we had previously used to monitor α5β1 trafficking in human ovarian carcinoma A2780 cells." (PMID 19175293, 2009). "Preclinical studies have suggested that NRP-1 expression is up-regulated in ovarian cancer tissue and correlates with advanced FIGO stage and lymph node metastasis." (PMID 36338759, 2022). "However, NRP-1 expression in ovarian cancer tissue failed to predict bevacizumab response in a retrospective analysis of the GOG-0218 clinical trial." (PMID 36338759, 2022). "Similarly, targeting neuropilin-1 (NRP1), a transmembrane receptor that contributes to cell contact evasion and tumorigenesis in ovarian tumors, with the miRNA miR-200c, induces sensitization of resistant SKOV3 ovarian cancer cell lines (BRCA wild-type) to olaparib." (PMID 35800369, 2022).
medulloblastoma (25 papers, 2010 to 2026). A malignant, invasive embryonal neoplasm arising from the cerebellum. "Overall, our study provides the first evidence for the expression of NRP1 by tumor-associated microglia/macrophages (TAMs) and endothelial cells in the microenvironment of medulloblastoma tumors." (PMID 40805120, 2025). "On the other hand, proteins like NRP1, known to be associated with various pediatric brain tumors and often overexpressed in medulloblastomas, rendered counterintuitive estimates in this context." (PMID 38350915, 2024). "A later study, however, demonstrated the association of NRP1 with medulloblastoma CSCs and its involvement in their self-renewal." (PMID 30678134, 2019). "Another study implicated PlGF, a VEGF family member, and PlGF/NRP1 signaling in the aggressive behavior of medulloblastoma." (PMID 30678134, 2019). "NRP1 expression in medulloblastomas was found to be associated with poor survival, with little or no expression in majority of the WNT tumors." (PMID 26097868, 2015). "Further, Kaplan-Meier survival analysis showed NRP1 expression in medulloblastomas to be associated with worse survival." (PMID 26097868, 2015). "Unexpectedly, in SHH and Group 3 medulloblastoma tumors, lower NRP1 transcript levels in medulloblastomas are associated with significantly shorter patient overall survival and may indicate poorer prognosis." (PMID 37894289, 2023). "In vitro radiosensitivity with MR438 could dependent not only on NRP1 expression but also to DNA repair mechanisms probably due to genetic alterations linked to medulloblastoma subgroups." (PMID 36457009, 2022). "Nevertheless, we believe that these observations provide the basis for future research to investigate the context-dependent role of NRP1 and TAMs in the medulloblastoma microenvironment and its potential impact on different molecular subgroups." (PMID 40805120, 2025). "Specifically, the mean MS2-intensity of NRP1 in controls was about 43 times higher than in medulloblastoma patients, possibly due to the extent incomplete data despite batch correction." (PMID 38350915, 2024). "Analysis of a set of 34 tumors with low NRP1 expression and 8 tumors with high NRP1 expression showed reduced survival in patients with high-expressing medulloblastomas." (PMID 37894289, 2023). "Inhibiting NRP1 function results in antitumor effects in experimental medulloblastomas by influencing cell survival, invasiveness, and stemness." (PMID 37894289, 2023). "Knockdown of NRP1 reduces the growth of orthotopic human D283 and D341 medulloblastoma xenografts, prevents spinal metastasis, and prolongs survival in mice without affecting cell proliferation by itself." (PMID 37894289, 2023). "In a set of 32 medulloblastoma tumors, 90% of samples representing different molecular subtypes showed marked expression of NRP1 expression." (PMID 37894289, 2023). "In these cells, the gene and signaling pathways that are common to several medulloblastoma lineages have been identified, such as NRP1, MSI1, TWIST1, MYCN, and OX2." (PMID 36982406, 2023). "Blocking NRP1 with specific antibodies prevents PlGF-induced activation of protein kinase-mediated signaling pathways in medulloblastoma cells." (PMID 37894289, 2023). "The effects of NRP1 inhibition in combination with radiotherapy were studied in an orthotopic medulloblastoma model by using medulloblastoma cells expressing luciferase transplanted into the right cerebellum." (PMID 36457009, 2022). "Inhibition of NRP‐1 interaction with placenta growth factor has antitumor effects in a mouse model of medulloblastoma." (PMID 34252269, 2022). "In the Sonic Hedgehog subgroup of medulloblastoma, PlGF binds to NRP1 leading to mitogen activated protein kinase (MAPK) signaling activation, tumor growth and dissemination." (PMID 32766254, 2020).
medulloblastoma (continued). "The tumor suppressive effect of miR-148a expression accompanied by the down-regulation of NRP1 makes miR-148a an attractive therapeutic agent for the treatment of medulloblastomas." (PMID 26097868, 2015). "In the present study as well, NRP1 expression was found to bring about almost complete rescue of miR-148a mediated inhibition of the invasion potential and tumorigenicity of medulloblastoma cells." (PMID 26097868, 2015). "Majority of the Group 3 tumors which are known to have the worse survival among the four medulloblastoma subgroups expressed NRP1." (PMID 26097868, 2015). "Downregulation of NRP1 expression has been shown to inhibit motility of medulloblastoma cells from Ptch1 (+/−) mice." (PMID 26097868, 2015). "MiR-148a expression in medulloblastoma cells brought about reduction in the expression of NRP1, a novel miR-148a target." (PMID 26097868, 2015). "Restoration of NRP1 expression in medulloblastoma cells was found to rescue the reduction in the invasion potential and tumorigenicity brought about by miR-148a expression." (PMID 26097868, 2015). "Kaplan Meier survival analysis of 62 medulloblastoma cases, showed that tumors with moderate or high NRP1 expression had significantly poorer overall survival (p = 0.0349; hazard ratio 6.06) than those having no detectable or low NRP1 expression." (PMID 26097868, 2015). "A study also demonstrated that increased expression of NRP1 correlates with the growth and spread of medulloblastoma, and with poor survival in patients with medulloblastoma." (PMID 25954957, 2015). "NRP1 expression was studied in a total of 93 medulloblastoma formalin fixed paraffin embedded (FFPE) tumor tissues by immunohistochemical analysis." (PMID 26097868, 2015). "Another study reported that NRP-1 was overexpressed in medulloblastoma (MB) and related to the undifferentiated status of MB and that an NRP-1 inhibitor (MR438) could stimulate the differentiation of MB stem-like cells." (PMID 38169627, 2024). "The idea of targeting the neuropilin-1 receptor has already been highlighted in two studies, which found that NRP1 blockade suppresses angiogenesis and medulloblastoma regression, decreases the rate of metastasis, and leads to better oncological outcomes in treated mice." (PMID 37371647, 2023). "In conclusion, the inhibition of NRP1 via MR438 could increase the radiosensitivity of medulloblastoma stem-like cells, especially at low doses." (PMID 36457009, 2022). "Several authors demonstrated that NRP1 depletion did not only affect cell proliferation but did affect other cell functions, such as cell differentiation, which strengthens our therapeutic approach based on the targeting of medulloblastoma stem-like cells." (PMID 36457009, 2022). "The medulloblastoma cells were positively identified by NRP-1 immunohistochemistry." (PMID 28463983, 2017). "NRP1 has recently been identified as a target gene of miR-148a in medulloblastoma." (PMID 26967387, 2016). "Thus, restoration of NRP1 expression rescued the reduction in the invasion potential brought about by miR-148a expression, indicating the role of NRP1 in the invasion ability of medulloblastoma cells." (PMID 26097868, 2015). "PlGF, a member of the VEGF-A family, activated the MAPK pathway via NRP1 in medulloblastoma." (PMID 26209534, 2015). "This indicates major role for NRP1 in miR-148a's tumor-suppressive effect on medulloblastoma cells." (PMID 26097868, 2015). "Finally, RNA-seq results showed that in pediatric medulloblastoma, Sema3 and Nrp1 expression levels are significantly elevated." (PMID 26371509, 2015). "Future studies should aim to characterize the activation state of NRP1+ TAMs in MB to determine whether NRP1 expression influences their pro- or anti-tumor effects and to elucidate their potential role in modulating angiogenesis within the medulloblastoma microenvironment." (PMID 40805120, 2025).
medulloblastoma (continued). "Consequently, we hypothesized that targeting NRP1 in medulloblastoma could improve current treatments." (PMID 36457009, 2022). "Hence, NRP1 expression is a useful marker for prognostication in medulloblastomas." (PMID 26097868, 2015). "Therefore, miR-148a mediated down-regulation of NRP1 could be an effective therapeutic strategy for the treatment of medulloblastomas as well as other cancers." (PMID 26097868, 2015). "Expression of microRNA miRNA-148a in non-WNT medulloblastoma cell lines reduces NRP1 expression and impairs proliferation, survival, invasiveness, and tumorigenicity." (PMID 37894289, 2023). "An immunohistochemical study showed NRP1 overexpression in five medulloblastoma samples in comparison with non-tumoral pediatric cerebellar tissue." (PMID 37894289, 2023). "In brain tumors, this is observed in GBMs (, present article) and medulloblastomas, although specifically in SHH and Group 3 tumors, shorter patient survival may be related to lower NRP1 transcript levels." (PMID 37894289, 2023). "In vitro results have demonstrated that PlGF, its receptor neuropilin 1 (Nrp1), and the MAPK signaling axis are critical for the survival of medulloblastoma cells, and in Smo/Smo transgenic mice, the blockade of PlGF with anti-PlGF antibodies was associated with significantly smaller tumors." (PMID 34436033, 2021). "The majority of medulloblastomas with constitutively active Wnt signaling does not express NRP1 due to a high expression of miR-148a, which downregulates NRP1 by binding to the 3′ untranslated region (3′-UTR) of its mRNA." (PMID 30717262, 2019). "One study concluded that the ability of NRP1 to mediate PlGF-stimulated growth of medulloblastoma requires its PDZ binding domain and is independent of VEGFR1 activity." (PMID 30678134, 2019). "Majority (75%) of the WNT subgroup medulloblastomas showed no detectable NRP1 expression, while only 23% Group 3 tumors lacked NRP1 expression." (PMID 26097868, 2015). "In the present study, majority (75%) of the WNT subgroup medulloblastomas lacked detectable NRP1 expression." (PMID 26097868, 2015). "We have previously shown that medulloblastoma stem-like cells could overexpressed NRP1 in vitro in relation to the expression of CSCs markers such as CD15 or CD133, and that inhibition of NRP1 induced a differentiated status of this specific tumoral population." (PMID 36457009, 2022). "To confirm the effects of NRP1 inhibition with MR438 on medulloblastoma stem cells, we evaluated the expression of stem cell markers (CD15, CD133 and Sox2) as well as the self-renewal ability of medulloblastoma cells to form medullospheres after tumor dissociation." (PMID 36457009, 2022). "Finally, our results highlighted that targeting NRP-1 with MR438 could be a potential new strategy to differentiate MB stem cells and could limit medulloblastoma progression." (PMID 29632646, 2018). "In medulloblastoma, tumor derived Sonic hedgehog (SHH) induces PlGF production in the cerebellar stroma, which promotes tumor cell survival through NRP1 independent of VEGFR1." (PMID 30717262, 2019).